ELOVL1 (ELOVL fatty acid elongase 1)
Description:
Catalyzes the first and rate-limiting reaction of the four reactions that constitute the long-chain fatty acids elongation cycle. This endoplasmic reticulum-bound enzymatic process allows the addition of 2 carbons to the chain of long- and very long-chain fatty acids (VLCFAs) per cycle. Condensing enzyme that exhibits activity toward saturated and monounsaturated acyl-CoA substrates, with the highest activity towards C22:0 acyl-CoA. May participate in the production of both saturated and monounsaturated VLCFAs of different chain lengths that are involved in multiple biological processes as precursors of membrane lipids and lipid mediators. Important for saturated C24:0 and monounsaturated C24:1 sphingolipid synthesis. Indirectly inhibits RPE65 via production of VLCFAs.
Synonyms: SSC1; CGI-88; IKSHD
Tractability: Small molecule: a high-quality ligand is known. Antibody: UniProt predicts a signal peptide or a membrane-spanning region. PROTAC: ubiquitination databases record sites on it; its protein half-life has been measured; a small molecule that binds it is known.
Target class: Enzyme; Transferase
Gene: Protein-coding gene on chromosome 1 (43,363,396 to 43,368,075, reverse strand). Ensembl gene ENSG00000066322.
Subcellular location: Endoplasmic reticulum membrane
Subcellular location (Human Protein Atlas): Endoplasmic reticulum
Pathways (Reactome):
Metabolism: Linoleic acid (LA) metabolism; Synthesis of very long-chain fatty acyl-CoAs; alpha-linolenic acid (ALA) metabolism
Gene Ontology:
Molecular function: fatty acid elongase activity; protein binding
Biological process: fatty acid elongation, monounsaturated fatty acid; fatty acid elongation, saturated fatty acid; sphingolipid biosynthetic process; very long-chain fatty acid biosynthetic process; alpha-linolenic acid metabolic process; fatty acid elongation, polyunsaturated fatty acid; linoleic acid metabolic process; long-chain fatty-acyl-CoA biosynthetic process; ceramide biosynthetic process; establishment of skin barrier; fatty acid biosynthetic process; fatty acid elongation; unsaturated fatty acid biosynthetic process
Cellular component: endoplasmic reticulum; endoplasmic reticulum membrane; membrane
Genetic constraint (gnomAD): Loss-of-function variants: 10 observed, 39.73 expected, observed/expected ratio (o/e) 0.25, 90% interval 0.15 to 0.43. The upper end of that interval is the gene's LOEUF score, 0.43, which puts it in group 1 of 6, group 1 being the genes least tolerant of losing a copy. Missense variants: 256 observed, 371.87 expected, observed/expected ratio (o/e) 0.69, 90% interval 0.62 to 0.76. Synonymous variants: 133 observed, 131.04 expected, observed/expected ratio (o/e) 1.01, 90% interval 0.88 to 1.17.
Homologues: Orthologues: chimpanzee ELOVL1 (98% identical), dog ELOVL1 (96% identical), guinea pig ELOVL1 (94% identical), mouse Elovl1 (92% identical), rat Elovl1 (92% identical), pig ELOVL1 (91% identical), tropical clawed frog elovl1 (76% identical), zebrafish elovl1b (69% identical), zebrafish elovl1a (66% identical), Drosophila melanogaster Elovl7 (45% identical), Drosophila melanogaster CG31522 (44% identical), Drosophila melanogaster CG33110 (44% identical), and 13 more. Paralogues in human: ELOVL7 (58% identical), ELOVL4 (40% identical), ELOVL5 (34% identical), ELOVL2 (33% identical), ELOVL3 (25% identical), ELOVL6 (24% identical).
Diseases named in the same sentence as ELOVL1 in open-access papers:
ELOVL1 is named in the same sentence as 65 diseases in open-access papers, as found by Europe PMC text mining. Sharing a sentence is not in itself a finding about the gene and the disease. The quoted sentences say what the papers report.
breast carcinoma (9 papers, 2013 to 2025). "Certainly, the involvement of ELOVL1 in breast cancer metabolism need to be further elucidated to determine the feasibility of therapeutic approaches against this enzyme." (PMID 40759952, 2025). "To test the contribution of in situ elongation to the levels of VLCFA in BC tissue we analyzed ELOVL1 mRNA and protein levels in BC cancer and normal mammary gland tissues from breast cancer patients." (PMID 40759952, 2025). "Elongation of fatty acid is under the control of seven fatty acid elongases (Elovl) and expression of Elovl1 or Elovl6 is increased in breast cancer tissues." (PMID 36056008, 2022). "In earlier reports it has been shown that silencing of ELOVL1 reduced cell viability of breast cancer cells significantly and that inhibition of ELOVL7 resulted in drastic attenuation of prostate cancer cell growth." (PMID 26862848, 2016). "Silencing ELOVL1 can reduce the lipidomic profiles and viability of breast cancer cells." (PMID 36728187, 2023). "ELOVL1 is highly expressed in clinical breast cancer samples." (PMID 26862848, 2016). "Among the listed genes, BIRC5, SEC14L2, Thymidine kinase (TK1), ZNF385B, CLIC6, ELOVL1, CHAF1B and TFF1 have been reported to have a role in early detection of cancers, tumor progression and metastasis in most of cancer types including breast cancer." (PMID 31703592, 2019). "Although ELOVL1 was not upregulated in breast cancer comparing to paired normal breast, the gene silencing results demonstrated that ELOVL1 was essential for the growth of breast cancer cells." (PMID 35912257, 2022). "Meanwhile, several other risk model genes were identified in this study (ST6GALNAC4, PLPP2, ELOVL1, HACD1, VAPB, CERS2, ALDH3B2, and HACD3) have not yet been explored in depth in breast cancer." (PMID 36059802, 2022).
ichthyosis (5 papers, 2014 to 2025). Disorders of cornification that are characterized by visible scaling and/or hyperkeratosis of most or all of the skin. "Recessive ELOVL1 cause a recognizable disorder characterized by ichthyosis, developmental delay, and a movement disorder with progressive spasticity, head tremor, myoclonus, and dystonia." (PMID 40590574, 2025). "For those with ichthyosis, it was present at birth in the cases with homozygous ELOVL1 variants while it developed later during the first year of life in the two cases with heterozygous variants." (PMID 40590574, 2025). "We show that biallelic variants in ELOVL1 are associated with a unique and recognizable phenotype of hypomyelinating leukodystrophy, ichthyosis, and a complex movement disorder including progressive spasticity, head tremor, and myoclonus." (PMID 40590574, 2025). "In ELOVL1-mutated ichthyosis patients and in Elovl1-KO mice, shortening of the FA chain length of NS ceramides and reduction in acylceramide EOS levels were observed." (PMID 39125861, 2024). "The triad of hypomyelinating leukodystrophy, ichthyosis, and a movement disorder appears to be unique to ELOVL1‐related disorders." (PMID 40590574, 2025). "Interestingly, patients with Mitchell syndrome may present with a skin rash or ichthyosis similar to that observed in other conditions with impaired VLCFA production, such as ELOVL1 deficiency." (PMID 38357503, 2024).
psoriasis (5 papers, 2019 to 2024). An autoimmune condition characterized by red, well-delineated plaques with silvery scales that are usually on the extensor surfaces and scalp. "A psoriasis mouse model showed decreases in the expression of fatty acid elongases ELOVL1, ELOVL3, and ELOVL4 as well as ceramide synthase 3, which are all involved in the synthesis of ceramides exceeding 24 carbons." (PMID 38992724, 2024). "The expression of ceramide synthase 3 (CERS3) and elongases (ELOVL1 and 4) was reduced in psoriasis lesions compared to healthy skin." (PMID 32316273, 2020). "The mRNA expression of ELOVL1 and ELOVL4 significantly decreased in AD-like dermatitis, whereas ELOVL1 increased in psoriasis-like dermatitis." (PMID 30838224, 2019). "Although there are no data in PLWH, previous work found decreased ELOVL1 activity in other models of chronic inflammation, such as psoriasis." (PMID 35807127, 2022). "Stimulating the expression of ELOVL1 or 4 and CERS3 might be beneficial for psoriasis patients with an increased IFN-γ production." (PMID 32316273, 2020).
colorectal cancer (3 papers, 2021 to 2023). A primary or metastatic malignant neoplasm that affects the colon or rectum. "We noticed that the amount of nonesterified VLCFA species (FFA 26:0 and FFA 26:1) and VLCFA-TAG species harboring C24:0 or C26:0 as their acyl moiety was significantly decreased in HCT116 colorectal cancer cells transfected with ELOVL1 siRNA." (PMID 33731797, 2021). "Furthermore, the delta-9-sterol CoA desaturase (SCD1), and the elongation of very long fatty acids protein one (ELOVL1) involved in the desaturation of stearic to oleic acid, and their respective elongation, have also been shown to be upregulated in colorectal cancer." (PMID 37110166, 2023).
dry eye (3 papers, 2019 to 2026). "However, CEs and WEs, which are rich in saturated VLCFAs and VLCFAls, respectively, are shortened in Elovl1-deficient mice, leading to a dry eye-like phenotype." (PMID 32252890, 2020). "Although aged Elovl1−/−Tg(IVL‐Elovl1) mice exhibit corneal opacity because of chronic dry‐eye symptoms, we confirmed that the corneas of these mice exhibited no pathological abnormalities at 16 weeks of age, when the behavioral analyses were completed." (PMID 32123819, 2019). "We have previously reported that mice lacking the FA elongase gene Elovl1 show dry eye accompanied by palpebral ptosis and increased eye blinking, due to shortening of the chain length of meibum lipids." (PMID 32252890, 2020).
Obesity (3 papers, 2017 to 2023). Accumulation of substantial excess body fat. "Deactivating mutations in Elovl1 trigger hypomyelination, while deficiency of Elovl6 leads to general obesity in mice." (PMID 31766565, 2019). "Concomitantly, in red skeletal muscle induction of obesity by a diet rich in fatty acids significantly enhanced only ELOVL1 and ELOVL6 (+ 33.09%, + 35.54%, vs. the control group, respectively, p < 0.05)." (PMID 36879113, 2023). "We discovered that the expression levels of ELOVL3, ELOVL5 and ELOVL6 increased similarly to estimated elongase activity (P<0.05), while the mRNA expression level of ELOVL1 decreased during the first year after obesity surgery (P=6 × 10−5)." (PMID 28869586, 2017). "Moreover, induction of obesity by high-fat diet feeding markedly altered the expression of each examined isoform of ELOVL, namely ELOVL1, ELOVL3, and ELOVL6 (+ 65.04%, + 36.19%, − 37.34% and + 65.81%, vs. the control group, respectively, p < 0.05) in the white skeletal tissue." (PMID 36879113, 2023).
X-linked adrenoleukodystrophy (3 papers, 2015 to 2025). X-linked adrenoleukodystrophy (X-ALD) is a peroxisomal disorder resulting in cerebral demyelination, axonal dysfunction in the spinal cord leading to spastic paraplegia, adrenal insufficiency and in some cases testicular insufficiency. "This compound was originally developed as a potent and selective ELOVL1 inhibitor in the context of X-linked adrenoleukodystrophy (X-ALD) with well-characterized in vitro and in vivo activities 24,25." (PMID 41298489, 2025). "In a previous publication, ELOVL1 protein expression was reduced by 80% at six days using siRNA to knockdown ELOVL1 in X-linked adrenoleukodystrophy (X-ALD) fibroblasts." (PMID 26204830, 2015). "Elovl1 has been widely studied in brain diseases such as adrenoleukodystrophy and certain tumour types as an unfavourable prognostic marker." (PMID 40065102, 2025).
dermatitis (2 papers, 2019 to 2023). An inflammatory process affecting the skin. "In particular, the mRNA expression of ELOVL1 and CerS3 increased significantly in IMQ-induced dermatitis." (PMID 30838224, 2019). "In the present study, the expression of ELOVL1 and ELOVL4 was also downregulated in FAg-induced AD-like dermatitis, and the relative amount of CERs with long-chain FAs, C24-CER[NS] and C26-CER[NS], consistently decreased." (PMID 30838224, 2019).
dyslipidemia (2 papers, 2022 to 2026). "Both ELOVL1 and ELOVL6 are biomarkers associated with an increased risk of NAFLD in the HIV-negative population with metabolic syndrome." (PMID 35807127, 2022).
glioblastoma (2 papers, 2023). The most malignant astrocytic tumor (WHO grade IV). "According to the GEPIA portal, higher expression of Elovl3 is associated with a worse prognosis for glioblastoma patients, as is the case for Elovl1." (PMID 37046844, 2023). "ELOVL1 is an enzyme responsible for the elongation of SFA, and the expression of this enzyme is also associated with poor patient outcomes in glioblastoma." (PMID 37239243, 2023). "The expression level of Elovl1 is also related to patient prognosis; according to the GEPIA portal, higher Elovl1 expression in glioblastoma tumors is associated with a poorer prognosis." (PMID 37046844, 2023). "However, Elovl1 expression in male patients is lower, whereas, in female patients, it is higher in glioblastoma tumors than in healthy tissue." (PMID 37046844, 2023). "This could suggest that the expression of Elovl1 may increase in glioblastoma tumors, resulting in a reduction in the substrate for this elongase in the glioblastoma tumor." (PMID 37046844, 2023). "Furthermore, the expression of SLC27A3 in men was positively correlated with the expression of ELOVL1 in this region of the glioblastoma tumor." (PMID 37239243, 2023). "The expression of Elovl1 in glioblastoma tumors may decrease, remain at the same level, or, according to the analysis conducted on the GEPIA portal, increase when compared to healthy brain tissue." (PMID 37046844, 2023). "Expression data for ELOVL1, ELOVL3, ELOVL6, SCD, and FADS2 were obtained from raw data published in our previous papers, where we examined the expression of elongases and desaturases in glioblastomas." (PMID 37239243, 2023).
glioma (2 papers, 2022). A benign or malignant brain and spinal cord tumor that arises from glial cells (astrocytes, oligodendrocytes, ependymal cells). "Additionally, a higher expression of ELOVL3 in glioma is associated with a worse prognosis, and for ELOVL1, it is associated with a tendency toward a worse prognosis (p = 0.066)." (PMID 36291290, 2022).
hepatocellular carcinoma (2 papers, 2022 to 2023). A malignant tumor that arises from hepatocytes. "At least for ELOVL1, a higher expression in hepatocellular carcinoma results in cancer immune evasion, including an increased expression of programmed death-ligand 1 (PD-L1) and cytotoxic T-lymphocyte-associated protein 4 (CTLA4)." (PMID 36291290, 2022). "In the context of hepatocellular carcinoma (HCC), ELOVL1 appears to influence immune cell infiltration and the expression of immune checkpoint markers, such as programmed cell death-1 (PD-1) and cytotoxic T lymphocyte-associated protein-4 (CTLA-4)." (PMID 37981715, 2023).
paraplegia (2 papers, 2019 to 2022). Complete paralysis of the lower half of the body including both legs, often caused by damage to the spinal cord. "A decrease in sphingomyelin C26:1, as observed here, was also reported in Elovl1 mutated infant/adolescent patients’ fibroblasts and hypomyelination of central white matter explained the symptoms spastic paraplegia and central nystagmus." (PMID 36555176, 2022). "Whereas patients with this mutation suffered from spasticity of the lower legs and became wheelchair‐dependent, the defect in motor function in Elovl1−/−Tg(IVL‐Elovl1) mice did not involve paraplegia but was instead rather mild." (PMID 32123819, 2019).
alcoholic cirrhosis (1 paper, 2023). "The hepatocyte immunoreactivity of Elovl1 increases in liver sections from patients with alcoholic cirrhosis (n: 8) compared to healthy control livers (n: 8)." (PMID 36624475, 2023). "Elovl1 immunoreactivity increased in patients with alcoholic cirrhosis compared to controls." (PMID 36624475, 2023).
colitis (1 paper, 2023). Inflammation of the colon. "However, the possible regulation of ERβ on plectin, ELOVL1, and ChAT in colitis still needs more animal model experiments and clinical studies to investigate." (PMID 37569842, 2023).
colorectal tumors (1 paper, 2021). "A recent study has suggested that colorectal tumors exhibit significantly higher levels of 22-, 24-, and 26-carbon FAs, as well as higher levels of ELOVL1 and ELOVL6 enzymes." (PMID 34206240, 2021).
COVID-19 (1 paper, 2023). A disease caused by infection with severe acute respiratory syndrome coronavirus 2. "Furthermore, ELOVL1 deficiency can lead to neurological defects such as hypomyelination that would render the neuronal firing slow and less efficient and, therefore, could explain the fatigue experienced by COVID-19 patients, particularly in long COVID." (PMID 38002279, 2023).
deafness (1 paper, 2019). An inherited or acquired condition characterized by the complete loss of the ability to hear from one or both ears. "Recently, a de novo mutation in the ELOVL1 gene, which encodes fatty acid elongase, was identified in patients with neurocutaneous disorders involving skin ichthyosis and multiple neurological abnormalities, including hypomyelination, spastic paraplegia, and high‐frequency deafness." (PMID 32123819, 2019).
Hepatic steatosis (1 paper, 2023). Steatosis is a term used to denote lipid accumulation within hepatocytes. "Furthermore, inhibition of biliary Sct/SR signaling (associated with reduced DR) inhibits hepatic steatosis by down-regulation of the lipid biosynthesis gene elongation of very-long-chain-fatty acids (Elovl1) through increased biliary miRNA-125b coupled with decreased angiogenesis." (PMID 36624475, 2023).
hepatitis B (1 paper, 2018). "The lower level of nervonic acid in hepatitis B cirrhosis patients in comparison of hepatitis B patients indicate the ELOVL1 lower activity in hepatitis B cirrhosis patients, because ELOVL1 production of lignoceric acid and nervonic acid acyl-CoAs is essential for the synthesis of C24 sphingolipids." (PMID 29506525, 2018).
Hyperglycemia (1 paper, 2018). An increased concentration of glucose in the blood. "Clozapine caused robust reductions in hepatic ceramide and sphingolipid levels (p < 0.0001), upregulated CerS2 (p < 0.05) and ELOVL1 (+ 37%) and induced significant hyperglycemia (vs controls)." (PMID 29720183, 2018). "Clozapine causes a robust reduction in hepatic ceramide and sphingomyelin levels, coupled with a potentially compensatory upregulation of ceramide synthesising enzymes (CerS2 and ELOVL-1), in the presence of hyperglycemia and evidence of hepatic ER stress." (PMID 29720183, 2018).
hyperlipidaemia (1 paper, 2012). "We recently showed that bezafibrate (BF), a drug used for the treatment of hyperlipidaemia, reduces VLCFA accumulation in X-ALD fibroblasts by inhibiting ELOVL1, an enzyme involved in the VLCFA synthesis." (PMID 22911730, 2012).
hypomyelinating leukodystrophy (1 paper, 2025). "However, the movement disorder, including head tremor and myoclonus present in ELOVL1 patients would be atypical for a hypomyelinating leukodystrophy like PMD." (PMID 40590574, 2025).
liver cancer (1 paper, 2022). An epithelial or non-epithelial malignant neoplasm that arises from the liver. "In liver cancer, ELOVL1 and ELOVL3 were strongly associated with poor prognosis of HCC by survival analysis and differential expression analysis." (PMID 35912257, 2022). "Furthermore, the immunohistochemical chip of 113 liver cancer samples showed 68 cases of them displayed high expression of ELOVL1 levels and 45 cases displayed low ELOVL1 expression levels." (PMID 35912257, 2022).
liver cirrhosis (1 paper, 2024). "We strongly believe that understanding the reasons behind the upregulation of ELOVL1 and VLCFA could give us some insights into the molecular pathways of liver cirrhosis." (PMID 39125684, 2024).